RGMA (repulsive guidance molecule BMP co-receptor a)
Diseases named in the same sentence as RGMA in open-access papers (continued):
Sharing a sentence is not in itself a finding about the gene and the disease.
tumor (11 papers, 2014 to 2025). "rs62021480, the top SNP association at the RGMA locus, encodes a 3 prime UTR variant for the gene, which is a glycoprotein that guides developing axons and may act as a tumor suppressor." (PMID 38714721, 2024). "We further postulate that RGMa–Neogenin interactions may also constitute a novel tumour suppressor pathway." (PMID 27029596, 2016). "miR-210-3p inhibits the expression of repulsive guidance molecule A (RGMA), a negative regulator of angiogenesis and tumor metastasis." (PMID 37221555, 2023).
cancer (8 papers, 2013 to 2025). A tumor composed of atypical neoplastic, often pleomorphic cells that invade other tissues. "For instance, a repertoire of axon-guidance molecules (e.g. netrin-1, UNC5A, NEO1, RGMA) have been shown to be dysregulated in human cancers, including colorectal cancer." (PMID 29459716, 2018). "Other signature genes, including PTN, KLK4, RGMA and PIGR, have also been reported to be involved in cancer progression." (PMID 29642861, 2018). "Importantly, target genes involved in epithelium development (RGMA, SHANK3, PAX6, PFN1, WNT4) and cancer (CBL, CYCS, FGF7, IGF1R, PTEN, PIK3CD, WNT4) address to a further role in the onset of epithelial abnormalities and oncogenesis." (PMID 23936163, 2013).
neurological diseases (4 papers, 2021 to 2025). "In conclusion, RGMa represents a multifaceted therapeutic target across a broad spectrum of neurological diseases." (PMID 40244061, 2025). "RGMa-neogenin signaling is involved in the pathogenesis of diverse neurological disorders and inhibition of RGMa exert beneficial effects." (PMID 33589594, 2021).
neurodegenerative disease (2 papers, 2020 to 2023). A disorder of the central nervous system characterized by gradual and progressive loss of neural tissue and neurologic function. "RGMa up-regulation was reported in an animal model of neurodegenerative diseases, such as Parkinson’s disease (PD), in which anti-RGMa antibodies have therapeutic potential." (PMID 37992159, 2023).
infection (1 paper, 2019). The state of being infected such as from the introduction of a foreign agent such as serum, vaccine, antigenic substance or organism. "Interestingly, differences in cytokine and chemokine expression existed between EBOV/Makona-preMA and EBOV/Makona-rgMA-2357 despite their shared replication deficiency in mice, suggesting that the additional 2357 mutation in NP may play a role in modulating the host response to infection." (PMID 31717793, 2019).
renal disease (1 paper, 2021). "By utilizing a custom target NGS 70-gene panel and a validation cohort, we have been able to point out some of these rare variants in the MYH9, CNDP1, SOWAHB and RGMA genes relevant to renal disease in diabetic patients." (PMID 34946941, 2021).
RGMA also shares sentences with these, for which no sentence is quoted: peritonitis (3 papers); Intellectual disability (2); acute lung injury (1); anemia (1); central nervous system diseases (1); cerebral small vessel disease (1); cognitive decline (1); Gait ataxia (1); glioblastoma (1); hyperthyroidism (1); Immunodeficiency (1); intracranial hypertension (1); ischemia (1); lung injury (1); lymphoma (1); Myelopathy (1); neurodevelopmental disorder (1); ovarian carcinoma (1); Parkinson disease (1); primary biliary cholangitis (1); psoriasis (1); rheumatoid arthritis (1); systemic lupus erythematosus (1); temporal lobe epilepsy (1); Truncal obesity (1).